C3 (complement C3)
Diseases named in the same sentence as C3 in open-access papers (continued):
Sharing a sentence is not in itself a finding about the gene and the disease.
diabetes (continued). "Our results indicate that C3 expression increased in the HG‐induced astrocytes as well as in the diabetic mice brain via RAGE‐p38MAPK‐NF‐κB signalling, which could be a potential target to prevent diabetes associated neurodegenerative pathology." (PMID 30246940, 2018). "This was however identified as due to the role of C3 in the adaptive immune system, as multiple low dose-STZ induces a form of diabetes that is transferable via adoptive transfer of T cells from a multiple low dose-STZ-treated to an untreated mouse." (PMID 38346191, 2024). "Many studies have shown that complement C3 levels were higher in multiple metabolic diseases, including obesity, diabetes, and NAFLD, and an energy-restricted diet decreased plasma C3 levels in men with obesity." (PMID 38044448, 2023). "The combination of C3 deposits and RPS class allows for a more accurate prediction of the time to diabetic ESRD." (PMID 35711407, 2022). "In this study, we compared the levels of C3 and its fragments in the blood of non‐diabetic individuals, T2DM patients, periodontitis patients and diabetic periodontitis patients." (PMID 32794619, 2020). "In addition to their roles in innate immunity, an emerging body of literature suggests that intact C3 and C5 complement proteins, and the cleaved C3a and C5a peptides, are important in regulating whole body metabolism, energy homeostasis and the pathogenesis of diabetes and metabolic syndrome." (PMID 28921001, 2018). "80% (20/25) of C3+/+ mice were exposed to hyperglycemia by 5th week after STZ administration, while all (30/30) of C3−/− mice were still diabetes-free survival by 6th week." (PMID 23824734, 2013). "Both human and animal studies determined that plasma levels of C3, C4, C4b, iC3b, MBL, MASP-2, C5b-9 Factor B, and Bb were found to be significantly increased in diabetes condition and have a role in exacerbating the pathophysiology of diabetes mellitus." (PMID 38564496, 2024). "The results showed that 17 variables, including BMI, DBP, neutrophil count, albumin, serum creatinine, eGFR, serum cystatin C, triglycerides, serum IgG, serum C3, UPE, hematuria, CKD stage, nephrotic syndrome, diabetes, T, and C, were statistically significant factors (P < 0.05)." (PMID 39494280, 2024). "Human pancreatic islets highly express intracellular C3, and C3 binds autophagy-related protein 16-1 (ATG16L1), thus regulating autophagy and contributing to β cell survival in human islet inflammation and diabetes." (PMID 36969185, 2023). "In the Cohort on Diabetes and Atherosclerosis Maastricht (CODAM), studies on plasma C concentrations (C3, properdin, factor H, factor D, C3a, Bb) and lipoprotein subclass profile (as measured by nuclear magnetic resonance spectroscopy) were performed in 523 participants." (PMID 37629447, 2023). "Despite all this evidence for involvement of complement component C3 and the glycosylation process in the pathogenesis of diabetes complications, C3 N-glycome has never been investigated in such population." (PMID 37293493, 2023). "Induction of diabetes with streptozotocin in female wildtype (WT) C57BL/6J and C3−/− mice showed that the lack of C3 attenuated the diabetes-induced increase of kidney-to-body weight ratio and glomerular basement membrane thickness in the diabetic kidneys." (PMID 34806406, 2022). "Glomerular C3 deposits have been detected increased in type 1 diabetes mellitus non-obese diabetic mouse and in OVE26 diabetic mouse." (PMID 34941814, 2021). "In addition, we found increased turnover rates of C3, the HDL protein involved in complement activation in the early stages of diabetes." (PMID 32235466, 2020). "Furthermore, C3−/− MDSC actively suppressed diabetogenic T cell proliferation and prevented/delayed the development of diabetes in arginase and/or iNOS-dependent manner." (PMID 23824734, 2013).
diabetes (continued). "Further, a significantly high C3 deposition in the capillary wall along with thickening of basement membranes and co-localization of CFH expression with CD11b+ve activated microglial cells in diabetic retina suggested microglia as a source of CFH in diabetic retina." (PMID 32117292, 2020). "We hypothesize that myeloid-derived suppressor cells (MDSC), which act as regulators in autoimmunity, play a role in resistance to diabetes in absence of complement C3." (PMID 23824734, 2013). "Furthermore, it is suggested that C3 serum levels could differentiate patients with DKD from patients with diabetes without kidney damage." (PMID 38338666, 2024). "First, it was shown that T2DM patients had elevated C3 in their blood and GCF and also had worse periodontal conditions compared to individuals without diabetes." (PMID 38614881, 2024).
glomerulonephritis (91 papers, 2008 to 2026). A renal disorder characterized by damage in the glomeruli. "The biopsy showed focal necrotizing and crescentic glomerulonephritis with mesangial proliferative changes and C3 deposits (active COVID-19 infection-associated)." (PMID 40429298, 2025). "It is important to differentiate bacterial-associated PICG from infection-associated glomerulonephritis, as the latter is histologically defined by endocapillary proliferation and prominent C3 deposition." (PMID 40755685, 2025). "C3 represents the most common complement component found in MPO-ANCA-associated glomerulonephritis [60,]." (PMID 38445024, 2024). "Streptococcal infection associated glomerulonephritis is more common in children with acute nephritis syndrome and decreased complement C3." (PMID 39969315, 2024). "The key to differentiate from C3G is that complement C3 in C3G often decreases continuously, while the decrease of C3 level in patients with staphylococcal infection associated glomerulonephritis is often temporary." (PMID 39969315, 2024). "The presence of C3 deposits have been associated with a worse outcome in ANCA glomerulonephritis and complement activation, particularly the alternative pathway, has emerged as being crucial in the development of AAV." (PMID 38445024, 2024). "Another important observation of this study is that highly noxious extracellular histones as potential causative agents for glomerular nephritis and acute kidney injury are bound to C3a/C3." (PMID 31871840, 2019). "In human anti-GBM disease, IgG1 auto-antibodies that bind to α345(IV) collagen in the human GBM (usually specific for α3NC1) cause severe glomerulonephritis, often featuring C3 deposition along the GBM." (PMID 29988342, 2018). "CCPs 1–4 of FH bind C3b (but not iC3b/C3d), are crucial for FI cofactor and C3bBb decay-accelerating activities, and harbor mutations or single nucleotide polymorphisms linked to age-related macular degeneration, aHUS, and C3 glomerulonephritis." (PMID 26459349, 2015). "Factor H deficient (fH-/-) mice develop spontaneous glomerulonephritis characterized by abundant glomerular C3 fragments." (PMID 26309728, 2015). "It is reported that glomerulonephritis associated with IE and glomerulonephritis associated with visceral infection especially secondary to staphylococcal infection include the glomerular lesions with dominant C3 deposition." (PMID 25506445, 2014). "This is in contrast to the effect of CFH deficiency, which results in the development of glomerulonephritis in CFH knockout mice due to uncontrolled C3 activation." (PMID 21637784, 2011). "Factor H (CFH)-deficient (Cfh−/−) mice spontaneously develop C3 deposition along the glomerular basement membrane (GBM) with subsequent development of glomerulonephritis with features of DDD, a lesion dependent on C3 activation." (PMID 19411110, 2009). "It is known that complement activation, particularly of components C3 and C4, has been implicated in the inflammatory processes that exacerbate renal injury, which is observed in conditions such as glomerulonephritis and chronic inflammation associated with CKD." (PMID 41516410, 2026). "Paradoxically, the intact C3 in these C1q-deficient mice could augment the alternative complement pathway, thereby exacerbating glomerulonephritis." (PMID 41155225, 2025). "For example, in a preclinical study of glomerulonephritis induced by the anti-basement membrane antibody, treatment with leflunomide was associated with alleviated glomerular lesions and reduced deposits of rat IgG and C3 along the glomerular capillary wall." (PMID 35786300, 2022). "Its harmful effect may be caused by deposition of immunocomplexes, IgM and C3 molecules in mesangial areas characterizing glomerulonephritis." (PMID 30118505, 2018). "Morphology of glomerulonephritis with dominant C3 deposits may underlie both post-infectious glomerulonephritis and C3 glomerulopathy, a recently introduced pathological entity." (PMID 26746693, 2016).
glomerulonephritis (continued). "Our patient had IE associated with septic pulmonary embolism, and it is reported that some of glomerulonephritis associated with IE and glomerulonephritis associated with visceral infection also show the glomerular lesions with dominant C3 deposition similar to that in our case." (PMID 25506445, 2014). "In all of the cases of MRSA infection-associated glomerulonephritis identified by our research group, the deposition of IgA has been remarkable; this feature differs from those of typical postinfection nephritis, which is characterized by glomerular deposition of either C3 and IgG, or of C3 only." (PMID 35806487, 2022). "Immunohistochemistry of renal biopsy showed granular C3 deposition on the glomerulus, consistent with glomerulonephritis." (PMID 41155225, 2025). "Glomerulonephritis and interstitial mononuclear cell infiltrations were observed in the kidneys, with increased IgG and C3 deposits in the glomeruli." (PMID 39939342, 2025). "Immunofluorescence studies were negative for immunoglobulin and complement deposition (IgG, IgM, IgA, C3, C4, kappa, and lambda), confirming the pauci-immune nature of glomerulonephritis." (PMID 40688963, 2025). "Regarding the three patients with a C3 glomerulonephritis, and an immune complex-mediated glomerulonephritis, serum complement C3 and C4 levels were normal." (PMID 39099564, 2024). "Immunoglobulin A (IgA) nephropathy is the most common type of glomerulonephritis worldwide and is characterized by mesangial deposits of IgA1, often with co-deposits of Complement component 3 (C3)." (PMID 37038123, 2023). "Patients with AAV having IC deposits were more likely to have hypocomplementemia than those with classical pauci-IC glomerulonephritis, consistent with our result, that is, the IC group had lower levels of complement C3." (PMID 36000886, 2022). "On the contrary, IE-related glomerulonephritis typically presented with endocapillary and/or mesangial hypercellularity with frequent crescent formation and C3-dominant immune deposits on immunofluorescence." (PMID 35243934, 2022). "The C3G definition includes presence of glomerulonephritis with C3-dominant immunofluorescence staining: C3 intensity must be at least two orders of magnitude more than any other immunoreactant." (PMID 36846022, 2022). "In contrast to the other groups, TG pristane-treated mice showed IgG and C3 deposits within the glomeruli, suggesting that glomerulonephritis had already progressed." (PMID 34381063, 2021). "C3-glomerulonephritis can lead to progressive renal impairment from complement-mediated glomerular injury." (PMID 32943008, 2020). "C3-dominant glomerulonephritis is defined as C3 deposition in renal tissue of at least two orders of magnitude greater than that for any other immunoreactant (including Ig, C4, C1q, etc.)." (PMID 31947692, 2020). "Of 31 biopsies with predominant C3 staining, 10 fulfilled histological criteria for C3 glomerulonephritis, while the remaining 21 cases were used as C3 Controls." (PMID 32652953, 2020). "C4NeF was first detected in a case of patients with postinfection glomerulonephritis and who had persistent low levels of C3 and C5, and it was also discovered in a case of MPGN." (PMID 31947692, 2020). "It is important to distinguish C3 deposition in C3 GN from other forms of glomerulonephritis, such as postinfection glomerulonephritis, in which immunoglobulin deposition occurs in the first phase of the disease and then disappears." (PMID 31947692, 2020). "Complement component 3 (C3) glomerulopathy, which includes dense deposit disease (DDD) and C3 glomerulonephritis, is caused by dysregulation of the alternative complement pathway." (PMID 29724182, 2018). "The high levels of autoantibodies in infected mice was associated with markedly accelerated renal disease, evidenced by increases in proteinuria, IgG2a and C3 kidney deposits, and glomerulonephritis (GN) scores." (PMID 30199535, 2018).
glomerulonephritis (continued). "Complement component 3 (C3) glomerulopathy, which includes dense deposit disease (DDD) and C3 glomerulonephritis, is a recently described disease entity caused by dysregulation of the alternative complement pathway." (PMID 29724182, 2018). "Kidney biopsy showed the presence of C3 glomerulonephritis, with exclusive deposits of C3 visible on immunofluorescence and a membranoproliferative pattern on light microscopy." (PMID 29884135, 2018). "Given that C3G is defined by predominant glomerular C3 deposition (two orders greater than immunoglobulins), other glomerulonephritis types, particularly those that are immune complex-mediated, occasionally fit this criterion, too." (PMID 27878657, 2017). "In fact, glomerulonephritis with “dominant staining of C3 defined as at least two orders of C3 intensity greater than that of any other immune reactant” without DDD-like deposits by EM is automatically classified as C3GN." (PMID 27878657, 2017). "Mesangial C3 deposition is seen in primary and secondary glomerulonephritis and in collagen diseases." (PMID 27460033, 2016). "C3 glomerulonephritis results from deposition of C3 degradation products and terminal complement components in glomeruli that result from the activation of alternative complement pathway due to the defects of complement-regulating proteins." (PMID 27460033, 2016). "Our previous studies have also shown such deposits of C3 in the glomerulus, beginning at about three weeks after induction of glomerulonephritis." (PMID 18836527, 2008). "The association of C3 rs2230199 with CKD was investigated in two retrospective cohorts, one composed of 514 CKD patients (stages 3–5) and 454 matched controls, and the second of 269 glomerulonephritis (GN) patients." (PMID 39857298, 2025). "Reduced C3 levels and complement deposition in glomeruli as features of glomerulonephritis were well established before; all these may support a role for neutrophil-activated complement replacement pathways in the pathogenesis of AAV." (PMID 36244021, 2023). "The biopsy showed acute tubular injury with myoglobin casts (rhabdomyolysis-associated) and diffuse tubular degenerative and regenerative changes, mild interstitial fibrosis, and superimposed C3 mesangial deposits suggestive of resolving infection-related glomerulonephritis." (PMID 37963892, 2023). "Mesangial expansion results from excessive production of extracellular matrix and deposition of immunoglobulins (Ig) or immune complexes, that is attributed mainly to glomerulonephritis (GN) (secondary membranous, complement 3 (C3), fibrillary), monoclonal Ig deposition and dense-deposit disease." (PMID 35176122, 2022). "For example, CFI deficiency can cause C3GN in humans, whereas CFI knockout does not cause spontaneous glomerulonephritis and proteinuria, but does result in mesangial C3 deposition and expansion in a portion of the knockout mice." (PMID 34149444, 2021). "Kidney biopsy showed the presence of C3 glomerulonephritis, with exclusive deposits of C3 visible on immunofluorescence, a membranoproliferative pattern on light microscopy and electron dense deposits in sub-epithelial, intramembranous, sub-endothelial and mesangial regions by electron microscopy." (PMID 31823738, 2019). "Complement C3 can act as a biomarker of IgA nephropathy and glomerulonephritis." (PMID 28560103, 2017). "Indeed, glomerulonephritis with prominent C3 deposition, as seen in our patient, is a common biopsy finding in kidney injury related to endocarditis." (PMID 27313916, 2016). "Nevertheless, a few mice with mild-to-moderate or moderate glomerulonephritis were present only in the saline-treated control group and the fluorescence intensity of C3 deposition in all treatment groups was significantly lower than in the saline-treated control group." (PMID 27924862, 2016).